IL1B (interleukin 1 beta)
Diseases named in the same sentence as IL1B in open-access papers (continued):
Sharing a sentence is not in itself a finding about the gene and the disease.
vitiligo (continued). "The findings showed that patients with active vitiligo had increased levels of ROS, high levels of MDA, AND IL‐6, TNF‐a, IL‐1b, IFN, and IL‐8." (PMID 39313936, 2024). "IL-1β, HMGB1, IL-8, and IL-6 TNF-α are believed to have a crucial role in the innate immune response, and their levels were considerably increased in vitiligo patients' serum and skin." (PMID 36920542, 2023). "In the present study, we observed increased levels of IL-8, IL-6, TNF-α, IFN-γ and IL-1β in the skin of monobenzone-induced vitiligo mice, and LBP significantly inhibited secretion of IL-8, IL-6, TNF-α, IFN-γ and IL-1β." (PMID 36655287, 2023). "In patients with vitiligo, PBMCs can secrete proinflammatory cytokines such as IL-1β, IL-6, IL-8, and tumor necrosis factor (TNF)-a, and infiltrate around the lesions of vitiligo, suggesting that PBMCs play important roles in the pathogenesis of vitiligo." (PMID 34941177, 2021). "Some NLRs, such as NLRP1 and NLRP3, are activated in response to oxidative stress or cellular damage in vitiligo; NLRP1 and NLRP3 are components of the inflammasome complex that, once activated, releases caspase 1 and IL-1β and IL-18." (PMID 34768860, 2021). "Although the drugs targeting IL-1β have been used in some NLRP3-related diseases, the concerns regarding this treatment in vitiligo existed." (PMID 32754591, 2020). "Interfering with Mfsd4a in melanocytes co-cultured with vitiligo model T cells significantly improved melanocyte activity, inhibited the levels of inflammatory cytokines TNF-α, IL-1β, and IL-6, reduced melanocyte apoptosis, and inhibited JAK/STAT3 pathway activation." (PMID 40707941, 2025). "Remarkably, the expression of NLRP1 and IL-1β was almost absent in lesional skin of vitiligo patients, similar to that in the skin of healthy control subjects." (PMID 37325658, 2023). "To assess whether LBP influences innate immune responses in the skin of mice with monobenzone-induced vitiligo, we measured IL-8, IL-6, TNF-α, IFN-γ and IL-1β expression by RT-qPCR." (PMID 36655287, 2023). "The macrophage migration inhibiting factor (MIF) is a protein that promotes the activation of immune cells and the production of other proinflammatory cytokines such as TNF‐α, IL‐1β, and IFN‐γ, which have proposed to play an essential role in the pathogenesis of vitiligo." (PMID 32705792, 2020). "Also, it is characterized by the fact that it allows the activation of immune cells and the production of proinflammatory cytokines such as TNF‐α, IL‐1β, and IFN‐γ, which have proposed to play an essential role in the pathogenesis of vitiligo." (PMID 32705792, 2020). "In another study, the expression levels of NLRP1 and IL-1β in perilesional vitiligo/non-segmental vitiligo skin were found to be significantly associated with disease progression." (PMID 29915579, 2018). "We have explored the role of Interleukin (IL)-1 in vitiligo by monitoring the expression of IL1A, IL1B, IL1Receptor1 (R1) and IL1 Receptor Antagonist (RN) in skin samples, effect of IL1-α on melanocyte viability, IL1R1 membrane expression and genotyping of IL1RN VNTR in Gujarat population." (PMID 27454254, 2016). "Significant increase of IL1B in non-lesional skin indicates its important role in vitiligo progression." (PMID 27454254, 2016). "IL1B is the predominant form of IL1 being produced and secreted by activated macrophages, monocytes, dendritic cells, natural killer (NK) cells and B cells, thereby potentially contributing to the autoimmune pathogenesis of vitiligo via inflammosome formation." (PMID 25221996, 2014). "Moreover, IL‐1β and IL‐18 can directly induce apoptosis (cell death) in melanocytes or disrupt their function, leading to depigmentation in vitiligo, which increased after using MBEHQ by vitiligo patients of this study." (PMID 39313936, 2024).
vitiligo (continued). "Overall, while the direct relationship between hydroquinone, MBEHQ, oxidative stress as well as IL‐1β, and IL‐18 with vitiligo is not well‐established, it is possible that these depigmenting agents could indirectly more stimulate the immune responses." (PMID 39313936, 2024). "Another hypothesis is that HLA-G expressed on the skin of vitiligo patients interacts with KIR2DL4 receptors from NK cells, and this interaction may induce the production of proinflammatory cytokines such as IFN-γ, TNF-α, IL-1α, IL-1β, IL-6, and IL-8." (PMID 31505868, 2019). "As IL-1β is the essential cytokine to develop Th17 cells, IL-1β produced by activated inflammasome may involve the development of nonsegmental vitiligo." (PMID 21804820, 2011). "Thus, to verify if Ins and IGF-1 evoke a pro-inflammatory feature in vitiligo keratinocytes and the possible role in immunopathogenesis, we quantified the amount of several secreted interleukins that demonstrated increased quantities of CXCL10, IL-6, IL-8, IL-1α, IL1-β, and TNFα." (PMID 40277891, 2025). "Moreover, IL1B is a potent activator of superoxide dismutase 2 (SOD2) in different tissues and cell types; which could lead to increased H2O2 production as observed in vitiligo patients." (PMID 25221996, 2014).
meningitis (43 papers, 2007 to 2025). A disorder characterized by acute inflammation of the meninges of the brain and/or spinal cord. "The expression of IL-1α and IL-1β in the CSF correlated with symptoms (inflammation and fever) linked to both encephalitis and meningitis groups." (PMID 40517242, 2025). "The CP isolated from piglets suffering from meningitis showed a clear inflammatory response by the increased expression (enhanced signal when referencing the GAPDH signal) of the genes encoding IL1β and IL8, as compared to the meningitis-free piglets." (PMID 33763387, 2021). "Intermediately, the EA ST28 strain MNCM43, which caused meningitis, induced a significant production of IL-1β, CCL2, and CCL3 only (p < 0.05)." (PMID 27409640, 2016). "In a recent study of 16 diagnostic markers of meningitis, only granulocytes, lactate, IL-6 and IL-1β in CSF exhibited similar reliability." (PMID 17386119, 2007). "To determine whether the immune system is affected by PLG and induces meningitis symptoms, we investigated the expression levels of EV-A71-associated cytokines such as IL-1β, IL-6, MCP-1, IL-10, and IFN-γ in serum after EV-A71 infection." (PMID 40377310, 2025). "High levels of TNF-α, IL-6 and IL-1β are characteristic of meningitis processes and may be associated with disease severity and the occurrence of sequelae." (PMID 21473761, 2011). "Inflammatory mediators upregulated in zebrafish, including TNF, IL-1β, and G-CSF, parallel those found in human CSF during meningitis." (PMID 40609050, 2025). "The serum of the PM mice also displayed significantly elevated levels of the inflammatory cytokines TNF‐α, IL‐6, and IL‐1β in serum and brain homogenates for the meningitis group." (PMID 39887961, 2025). "C-reactive protein (CRP), tumor necrosisfactor-α (TNF-α), interleukin-1β (IL-1β), interleukin-6(IL-6), procalcitonin (PCT) are considered beingclosely implicated in the presence and progression ofpurulent meningitis." (PMID 39139150, 2024). "Meanwhile, these factors were also elevatedin the control group compared to the healthygroup, which aligns with previous research and indicatesa clear elevation of that CRP, TNF-α, IL-6, PCT,and IL-1β in children with refractory purulent meningitis." (PMID 39139150, 2024). "Predictive efficacy of CRP, TNF-α, IL-6, PCT and IL-1β in children with refractory purulent meningitis treated with dexamethasone." (PMID 39139150, 2024). "The expression of TNF-α, IL-6, and IL-1β in the APEC XM group was in line with that previously reported in in vivo or in vitro E. coli meningitis studies." (PMID 34529552, 2021). "In CSF, higher concentration of IL-1β was observed in two patients with severe encephalitis than in three with meningitis, opposite to the tendency in serum." (PMID 28646884, 2017). "An attempt to switch from anakinra to the anti-IL-1β monoclonal antibody canakinumab (150 mg/8 weeks) resulted in a major disease flare requiring hospital admission for sterile meningitis." (PMID 29163488, 2017). "Previous works have investigated the CSF levels of inflammatory cytokines and chemokines in patients with meningitis, such as IL-6, IL-1β, TNF-α, IL-10, chemokines of the CXC family (IL-8) and growth factors using immunoenzymatic methods." (PMID 26040285, 2015). "It has been reported that in patients with meningitis, IL-1β expression levels are negatively correlated with prognosis, that is, a higher IL-1β expression level results in a poorer prognosis." (PMID 25780458, 2015). "Low levels of IL-1β, TNF-α or IL-6 in nasopharyngeal secretions were observed in children with recurrent episodes of acute otitis media, an important cause of meningitis." (PMID 26316174, 2015). "Levels of IL-1β and IL-18 were elevated in the CSF of patients with meningitis as compared to controls." (PMID 23902681, 2013). "Low levels of IL-1β, TNF-α and IL-6 in nasopharyngeal secretion were observed in children with recurrent episodes of acute otitis media, an important cause of meningitis." (PMID 21473761, 2011).
meningitis (continued). "Moreover, our investigations showed that A. cantonensis induces meningitis, hemorrhage, and vascular congestion in vivo and upregulates IL-1β and IL-6 secretion following ESP stimulation in astrocytes in vitro." (PMID 41284727, 2025). "Therefore, CRP,TNF-α, IL-6, PCT, and IL-1β can be applied as one ofthe crucial indicators to evaluate the curative effect ofrefractory purulent meningitis in children." (PMID 39139150, 2024). "Notably, CRP andIL-1β demonstrated superior predictive performance,suggesting that CRP, TNF-α, IL-6, PCT, and IL-1β canserve as effective indicators for evaluating efficacy ofdexamethasone treatment in children with refractorypurulent meningitis." (PMID 39139150, 2024). "Additionally, IL-1β intracerebral administration in adult rats induces meningitis, however in juvenile rats that are between 2 and 6 weeks old IL-1β has the secondary effect of increasing BBB permeability." (PMID 31293586, 2019). "As such, it may be hypothesized that pro-inflammatory mediators are highly concentrated in the CNS during meningitis and diluted in the bloodstream, which might explain the low systemic IL-1β levels detected during S. suis infection." (PMID 27409640, 2016). "Interestingly, production of IL-1β was clearly observed for the first time during the S. suis meningitis; levels of this cytokine are barely quantifiable during the systemic infection." (PMID 27409640, 2016). "This cytokine may play an important role during the S. suis meningitis, as has been reported for S. pneumoniae, where levels of IL-1β determine the outcome and severity of the disease." (PMID 27409640, 2016). "Similarly, Parp1 gene deletion and a PARP inhibitor reduce Il1β, Il6, and Tnf expression in the brain of mice infected with S. pneumoniae, and this is correlated with reduced meningitis-induced inflammation." (PMID 25161822, 2014). "Our previous study showed that the meningitis-associated E. coli strain PCN033 could infect astrocytes U251, induce rapid inflammatory responses, and promote the expression of many pro-inflammatory mediators such as IL-1β, IL-6, IL-8, TNF-α, MCP-1, and MIP-2." (PMID 33985523, 2021). "The results of our study indicated that in the meningitis mouse model constructed using S. pneumoniae serotype III, the NLRP3 inflammasome, ASC and caspase‐1, IL‐1β and IL‐18 expression all were increased." (PMID 39887961, 2025). "The levels of inflammatory cytokines, including interleukin (IL)-1α, IL-1β, IL-6, and TNF-α, in brain tissues were significantly elevated after meningitis induction compared with those in normal controls." (PMID 35888118, 2022). "During meningitis, the permeability of BBB and the expression of cytokines IL-1β, IL-6 and TNF-α increased." (PMID 36555174, 2022). "As expected, in the PFC, we observed increased levels of pro-inflammatory cytokines such as IL1-α, IL1-β, IL-6, IL-17, TNF-α, and INF-γ (P < 0.05) and decreased levels of IL-7, IL-10, and IL-13 (P < 0.05) in the 24-h meningitis group." (PMID 31901235, 2020). "The results from this study demonstrate a storm of inflammatory cytokines, such as IL1-α, IL-1β, IL-6, IL-18, TNF-α, and INF-γ, in the 24-h meningitis group." (PMID 31901235, 2020). "In the hippocampus, we observed increased levels of pro-inflammatory cytokines, such as IL1-α, IL1-β, IL-6, IL-18, TNF-α, and INF-γ (P < 0.05) in the 24-h meningitis group." (PMID 31901235, 2020). "Here, we show for the first time that during meningitis cytokine and chemokine levels also positively correlate with the bacterial burden in the brain of wild-type mice (id est IL-6, TNF-α, IL-1β, IL-10, KC, and MIP-2)." (PMID 25958220, 2015). "We have also demonstrated the production of other inflammatory cytokines in the brain during meningitis by TIGR4, as indicated by the TNF-α and IL-1β relative gene expression increase." (PMID 26648922, 2015).
meningitis (continued). "Notably, in experimental meningitis, PARP1-deficient mice and mice treated with the PARP inhibitor, 3 aminobenzamide (3-AB), display reduced leukocyte infiltration and meningeal inflammation, and this is correlated with impaired expression of Il1β, Il6 and Nos2." (PMID 25161822, 2014). "Homologous antibodies to TNF, IL-1α and IL-1β inhibited leukocytosis and brain edema and moderately decreased BBB permeability in this model of meningitis." (PMID 23997430, 2013). "When a panel of cytokines (including GM-CSF, IFNγ, IL-1α, IL-1β, IL-1ra, IL-2, IL-4, IL-6, IL-8, IL-10, IL-12, IL-18, and TNF-α) was measured in saliva from healthy pigs and in pigs with meningitis and S. suis infection, upregulation of several cytokines was observed in the diseased animals." (PMID 40284818, 2025). "The concentrations of the cytokines IFN-γ, IL-6 and TNF and the chemokine CCL2 were not significantly different between the WT and GKO meningitis animals, but a significantly lower concentration of IL-1β in the CSF was observed in the GKOs (p = 0.005)." (PMID 31700009, 2019). "In meningitis pathophysiology, BBB disruption is an obligatory outcome, accompanied by acute inflammatory responses, with the release of multiple inflammatory factors such as TNF-α, IL-1β, IL-6, IL-17A, MCP1, and GRO-α." (PMID 31783671, 2019). "Additionally, complement C1q and C3 are critical for the innate immune response to Streptococcus pneumoniae in the CNS, and C3−/− mice were shown to display reduced expression of IL-1β, IL-12 and MIP-1γ in the CNS in a meningitis animal model." (PMID 26822321, 2016). "High levels of the pro-inflammatory cytokines such as interleukin 1 beta (IL-1 beta), interleukin 6 (IL-6) and tumor necrosis factor alpha (TNF alpha), were detected in the cerebro-spinal fluid (CSF) of patients with meningitis, which is typical of the severe inflammation of the brain." (PMID 23874613, 2013). "Proinflammatory cytokines (IL-1β, IL-6, TNFα, MCP-1, MIP-1alpha, and RANTES) and adhesion molecules (CD44 and ICAM-1) were significantly reduced in the cerebrospinal fluids of the α7-/- mice with E. coli meningitis." (PMID 21966399, 2011). "However, an attenuated increase in CSF IL-1β concentration in TLR2/4 GKO mice in our meningitis mouse model did not confer protection from learning impairment in mice subjected to patrolling or reversal tasks." (PMID 31700009, 2019). "Therefore, the combination of significant pleocytosis with elevated levels of inflammatory mediators, such as IL-1β, CCL2, and CCL3, may differentiate modest procedure-related sterile meningitis from an active infection." (PMID 31262978, 2019). "Concentrations of MIF, TNFα, and IL-1β were measured with commercial ELISA in serum and cerebrospinal fluid (CSF) from 36 hospitalized TBE patients, 7 patients with non-TBE meningitis, and 6 controls." (PMID 28646884, 2017). "IL-1β serum concentration was significantly elevated both in TBE and non-TBE meningitis (p < 0.05)." (PMID 28646884, 2017).